MIR181A2 (microRNA 181a-2)
Synonyms: hsa-mir-181a; MIRN181A; MIRN181A2; hsa-mir-181a-2; mir-181a-2
Gene: MicroRNA gene on chromosome 9 (124,692,442 to 124,692,551, forward strand). Ensembl gene ENSG00000207595.
Gene Ontology:
Biological process: miRNA-mediated post-transcriptional gene silencing
Cellular component: RISC complex
Homologues: Orthologues: chimpanzee ptr-mir-181a-2 (100% identical), macaque mml-mir-181a-2 (99% identical), rat Mir181a2 (82% identical), pig ssc-mir-181a-2 (69% identical), guinea pig MIR181A2 (63% identical), tropical clawed frog xtr-mir-181a-2 (55% identical), dog MIR181A2 (54% identical), rabbit MIR181A2 (54% identical). Paralogues in human: MIR181A1 (58% identical), MIR181C (57% identical), MIR181B1 (41% identical), MIR181B2 (40% identical).